DNAI4 (dynein axonemal intermediate chain 4)
Description:
Plays a critical role in the assembly of axonemal dynein complex, thereby playing a role in ciliary motility.
Synonyms: WDR78; DIC4; FLJ23129
Tractability: Small molecule: a structure with a bound ligand is known.
Gene: Protein-coding gene on chromosome 1 (66,812,885 to 66,924,890, reverse strand). Ensembl gene ENSG00000152763.
Subcellular location: Cytoplasm, cytoskeleton, flagellum axoneme; Cytoplasm, cytoskeleton, cilium axoneme; Dynein axonemal particle
Subcellular location (Human Protein Atlas): Flagellar centriole; Mid piece; Principal piece
Gene Ontology:
Molecular function: dynein heavy chain binding; dynein light chain binding
Biological process: axonemal dynein complex assembly; cilium movement
Cellular component: axonemal dynein complex; axoneme; dynein axonemal particle; motile cilium
Genetic constraint (gnomAD): Loss-of-function variants: 60 observed, 86.28 expected, observed/expected ratio (o/e) 0.7, 90% interval 0.56 to 0.86. The upper end of that interval is the gene's LOEUF score, 0.86, which puts it in group 3 of 6, group 1 being the genes least tolerant of losing a copy. Missense variants: 895 observed, 902.45 expected, observed/expected ratio (o/e) 0.99, 90% interval 0.94 to 1.05. Synonymous variants: 315 observed, 299.19 expected, observed/expected ratio (o/e) 1.05, 90% interval 0.96 to 1.16.
Homologues: Orthologues: chimpanzee DNAI4 (97% identical), macaque DNAI4 (95% identical), dog DNAI4 (82% identical), pig DNAI4 (79% identical), rabbit DNAI4 (78% identical), mouse Dnai4 (71% identical), rat Dnai4 (70% identical), tropical clawed frog dnai4 (49% identical), zebrafish dnai4 (42% identical), Drosophila melanogaster Dic61B (19% identical), Drosophila melanogaster CG13930 (18% identical). Paralogues in human: DNAI1 (22% identical), DYNC1I2 (16% identical), DNAI3 (15% identical), DYNC1I1 (15% identical), DYNC2I1 (14% identical), DNAI2 (12% identical), DYNC2I2 (12% identical).
Diseases named in the same sentence as DNAI4 in open-access papers:
DNAI4 is named in the same sentence as 8 diseases in open-access papers, as found by Europe PMC text mining. Sharing a sentence is not in itself a finding about the gene and the disease.
DNAI4 shares sentences with these, for which no sentence is quoted: cancer (4 papers); Hydrocephalus (2); adenoma (1); ciliopathy (1); colon cancer (1); Infertility (1); metastatic prostate carcinoma (1); tumor (1).